SNORD115-6 (small nucleolar RNA, C/D box 115-6)
Synonyms: HBII-52-6
Gene: Small nucleolar RNA gene on chromosome 15 (25,180,497 to 25,180,578, forward strand). Ensembl gene ENSG00000200812.
Gene Ontology:
Biological process: RNA processing
Cellular component: nucleolus
Homologues: Orthologues: chimpanzee SNORD115 (98% identical), macaque SNORD115 (96% identical). Paralogues in human: SNORD115-11 (99% identical), SNORD115-29 (99% identical), SNORD115-34 (99% identical), SNORD115-36 (99% identical), SNORD115-42 (99% identical), SNORD115-43 (99% identical), SNORD115-12 (98% identical), SNORD115-15 (98% identical), SNORD115-16 (98% identical), SNORD115-22 (98% identical), SNORD115-26 (98% identical), SNORD115-30 (98% identical), and 37 more.